SCOC (short coiled-coil protein)
Description:
Positive regulator of amino acid starvation-induced autophagy.
Synonyms: SCOCO; HRIHFB2072; UNC-69
Tractability: Small molecule: a structure with a bound ligand is known. Antibody: UniProt places it where antibodies can reach, with high confidence. PROTAC: ubiquitination databases record sites on it.
Gene: Protein-coding gene on chromosome 4 (140,257,286 to 140,385,728, forward strand). Ensembl gene ENSG00000153130.
Subcellular location: Golgi apparatus membrane; Golgi apparatus, trans-Golgi network; Cytoplasm, cytosol
Subcellular location (Human Protein Atlas): Golgi apparatus; Nucleoplasm
Pathways (Reactome):
Vesicle-mediated transport: Retrograde transport at the Trans-Golgi-Network
Gene Ontology:
Molecular function: protein binding
Biological process: positive regulation of macroautophagy; regulation of protein complex stability
Cellular component: endosome; Golgi apparatus; Golgi membrane; trans-Golgi network; cytosol
Genetic constraint (gnomAD): Loss-of-function variants: 2 observed, 2.68 expected, observed/expected ratio (o/e) 0.75, 90% interval 0.29 to 1.79. That is too few expected variants to judge how well the gene tolerates losing a copy. Missense variants: 25 observed, 34.63 expected, observed/expected ratio (o/e) 0.72, 90% interval 0.52 to 1.01. Synonymous variants: 6 observed, 8.96 expected, observed/expected ratio (o/e) 0.67, 90% interval 0.37 to 1.32.
Homologues: Orthologues: chimpanzee SCOC (100% identical), dog SCOC (100% identical), guinea pig SCOC (100% identical), macaque SCOC (100% identical), mouse Scoc (100% identical), pig SCOC (100% identical), rat Scoc (100% identical), tropical clawed frog scoc (94% identical), zebrafish scocb (91% identical), zebrafish scoca (90% identical), Drosophila melanogaster CG5934 (67% identical), Caenorhabditis elegans unc-69 (60% identical).
Diseases named in the same sentence as SCOC in open-access papers:
SCOC is named in the same sentence as 6 diseases in open-access papers, as found by Europe PMC text mining. Sharing a sentence is not in itself a finding about the gene and the disease. The quoted sentences say what the papers report.
depression (1 paper, 2022). "Analyzing the protein regulatory network of FEZ1, in a series of interaction proteins obtained, it is found that the three autophagy-related proteins SCOC, ULK1, and NBR1 might play a role in depression." (PMID 35435132, 2022).
Sepsis (1 paper, 2023). Sepsis is defined as life-threatening organ dysfunction caused by a dysregulated host response to infection. "Among them, the AUCs of ITGAM, KIF1B, RRAGD, S100A9, SCOC, and SPTLC2 in the internal and external test sets were more than 0.6, indicating diagnostic significance for sepsis." (PMID 37834169, 2023).
cancer (1 paper, 2022). A tumor composed of atypical neoplastic, often pleomorphic cells that invade other tissues. "Importantly, in the HIF1A-knockout HepG2 cells, our qRT-PCR data confirmed the selected mRNA changes revealed by RNA-sequencing, and with TCGA pan-cancer data, we revealed that the expressional levels of these three genes, LUM, SCOC, and CCL2, were associated with immune cell infiltration levels." (PMID 35774500, 2022).
SCOC also shares sentences with these, for which no sentence is quoted: neuroendocrine tumor (1 paper); neuromuscular disease (1); Stroke (1).